DBNDD1 (dysbindin domain containing 1)
Synonyms: MGC3101; FLJ12582
Tractability: PROTAC: its protein half-life has been measured.
Gene: Protein-coding gene on chromosome 16 (90,004,871 to 90,019,890, reverse strand). Ensembl gene ENSG00000003249.
Subcellular location (Human Protein Atlas): Nuclear speckles; Cytosol; End piece; Equatorial segment; Mid piece; Principal piece
Gene Ontology:
Biological process: regulation of signal transduction
Cellular component: cytoplasm
Genetic constraint (gnomAD): Loss-of-function variants: 12 observed, 13.27 expected, observed/expected ratio (o/e) 0.9, 90% interval 0.58 to 1.46. The upper end of that interval is the gene's LOEUF score, 1.46, which puts it in group 6 of 6, group 1 being the genes least tolerant of losing a copy. Missense variants: 214 observed, 189.84 expected, observed/expected ratio (o/e) 1.13, 90% interval 1.01 to 1.26. Synonymous variants: 101 observed, 89.32 expected, observed/expected ratio (o/e) 1.13, 90% interval 0.96 to 1.33.
Homologues: Orthologues: macaque DBNDD1 (90% identical), dog DBNDD1 (85% identical), pig DBNDD1 (84% identical), guinea pig DBNDD1 (82% identical), mouse Dbndd1 (80% identical), rabbit DBNDD1 (77% identical), rat Dbndd1 (75% identical), tropical clawed frog dbndd1 (61% identical), zebrafish dbndd1 (48% identical), Caenorhabditis elegans dsbn-1 (11% identical), Drosophila melanogaster Dysb (8% identical). Paralogues in human: DTNBP1 (33% identical), DBNDD2 (22% identical).
Diseases named in the same sentence as DBNDD1 in open-access papers:
DBNDD1 is named in the same sentence as 27 diseases in open-access papers, as found by Europe PMC text mining. Sharing a sentence is not in itself a finding about the gene and the disease. The quoted sentences say what the papers report.
breast carcinoma (3 papers, 2008 to 2025). "(rs8059973, rs3785181) is on chromosome 16, where rs8059973 is in gene DBNDD1, rs3785181 is in gene GAS11. rs8059973/DBNDD1 is associated with breast cancer." (PMID 31888641, 2019). "Studies suggest that CIAPIN1 overexpression promotes breast cancer by regulating cell cycle and DNA replication, while DBNDD1 hypomethylation may contribute to tumor progression by affecting DNA synthesis or damage repair." (PMID 41048937, 2025). "Expression levels of the other two, dysbindin domain containing 1 (DBNDD1) and heat shock binding protein 1 (HSBP1) could be confirmed by RT-qPCR and may be the subject of future breast cancer research." (PMID 18416817, 2008).
melanoma (3 papers, 2022 to 2024). A malignant, usually aggressive tumor composed of atypical, neoplastic melanocytes. "For example, genes in cluster 2 (SPIRE2, SPATA2L), 3 (OCA2, DBNDD1, FANCA, GAS8) and 4 (URAHP, DEF8, CPNE7, MC1R) underlie the associations between melanoma and pigmentation traits." (PMID 38308491, 2024). "Melanoma is a skin ageing phenotype; DBNDD1 is downregulated in melanoma skin relative to adjacent normal skin (GSE44805, Expression Ratio = 0.84, p-Value = 2.10E−02)." (PMID 35907981, 2022).
Type 2 Diabetes (2 papers, 2023 to 2024). "Regarding DBNDD1 (Dysbindin Domain Containing 1), there is evidence of its involvement in gluco-metabolic pathways and through its function of binding dystrobrevin, a protein involved in intracellular processes in muscle tissue, has also some evidence for an involvement in type 2 diabetes." (PMID 35953519, 2024).
benign prostatic hyperplasia (1 paper, 2023). A non-cancerous nodular enlargement of the prostate gland. "Next, we validated DBNDD1 expression in GSE220942 (the role of GALNT7 upregulation in PCa cells) and GSE217260 (DEGs of benign prostatic hyperplasia and high-risk prostatic carcinoma tissues)." (PMID 37569304, 2023).
bipolar disorder (1 paper, 2023). A disorder of the brain that causes unusual shifts in mood, energy, activity levels and the ability to carry out day-to-day tasks. "The MetaCore analysis suggested that regulating GSK-3β in bipolar disorder was closely correlated with the DBNDD1 gene and its co-expressed genes in the progression of PCa." (PMID 37569304, 2023). "Consequently, GeneGo MetaCore’s annotations of biological processes revealed that DBNDD1 was significantly associated with a number of metabolic pathways, including the highest ranking of “regulation of GSK3-beta in bipolar disorder”, “ATP/ITP metabolism”, and “GTP-XTP metabolism”." (PMID 37569304, 2023). "Regulation of glycogen synthase kinase (GSK)-3β in bipolar disorder and ATP/ITP/GTP/XTP/TTP/CTP/UTP metabolic pathways was closely correlated with the DBNDD1 gene and its co-expressed genes in PCa." (PMID 37569304, 2023).
colorectal cancer (1 paper, 2026). A primary or metastatic malignant neoplasm that affects the colon or rectum. "This potential mechanism also corroborates our findings that higher DBNDD1 expression is linked to an increased risk of colorectal cancer." (PMID 41595533, 2026). "Moreover, DBNDD1 knockdown slowed tumor growth in vivo, highlighting the DBNDD1–GDF15–NF-κB signaling pathway as a driver of colorectal cancer pathogenesis." (PMID 41595533, 2026).
Hermansky-Pudlak syndrome (1 paper, 2016). Hermansky-Pudlak syndrome (HSP) is a multi-system disorder characterized by oculocutaneous albinism, bleeding diathesis and, in some cases, neutropenia, pulmonary fibrosis, or granulomatous colitis. "A disease association for DBNDD1 is not identified yet, but mutations in DTNBP1 are responsible for the Hermansky-Pudlak syndrome 7, which is characterized by oculocutaneous albinism, prolonged bleeding, and pulmonary fibrosis." (PMID 27034888, 2016).
liver cancer (1 paper, 2023). An epithelial or non-epithelial malignant neoplasm that arises from the liver. "While expression of DBNDD2 messenger (m) RNA was lower in all cancer types, expression of the DBNDD1 gene was significantly higher in numerous tumor types, including PCa, lung cancer, and liver cancer, among others." (PMID 37569304, 2023). "In our work, we focused primarily on analyzing DBNDD1 expression in the most prevalent male cancers; therefore, PCa, liver cancer, and lung cancer were chosen for further examination, and they also showed similar ratios of fold changes in DBNDD1 expression between normal and tumor tissues." (PMID 37569304, 2023).
lung adenocarcinoma (1 paper, 2023). A carcinoma that arises from the lung and is characterized by the presence of malignant glandular epithelial cells. "DBNDD1 gene expression was influenced by sample type, cancer stage, and promoter methylation levels of different cancers, such as PRAD, liver hepatocellular carcinoma (LIHC), and lung adenocarcinoma (LUAD)." (PMID 37569304, 2023).
lung carcinoma (1 paper, 2023). "Regarding tumor stages, metastasis, and OS rates, we found the effect of DBNDD1 gene expression to be more significant in PCa than in liver and lung cancers." (PMID 37569304, 2023).
lung squamous cell carcinoma (1 paper, 2023). "Most analyzed cancers exhibited high numbers of DBNDD1 genetic alterations of amplifications and copy number deletions, except lung squamous cell carcinoma which had complete mutations." (PMID 37569304, 2023).
prostate carcinoma (1 paper, 2023). A carcinoma that arises from epithelial cells of the prostate gland. "Consequently, E2F1, E2F4, and E2F5 had negative correlations with DBNDD1 expression in normal prostate tissues but positive correlations in prostate carcinoma tissues." (PMID 37569304, 2023).
prostate tumors (1 paper, 2023). "Overexpression of DBNDD1 protein levels was detected in prostate tumor tissue samples from the HPA database." (PMID 37569304, 2023). "To investigate DBNDD1 alterations involved in PCa, we next analyzed gene expression signatures of prostate tumor tissue samples versus solid normal tissue samples using GSE datasets." (PMID 37569304, 2023). "In our study, we attempted to determine links between the DBNDD1 gene and networks regulated by transcription levels and immune infiltration in PCa to assist in identifying a new potential immunotherapeutic target in the prostate tumor microenvironment (TME)." (PMID 37569304, 2023). "We visualized multiple genomic alteration events of the DBNDD1, DBNDD2, and DTNBP1 genes across a set of prostate tumor samples using OncoPrint using a query for alterations." (PMID 37569304, 2023). "Interestingly, we found that only DBNDD1 gene expression in the dysbindin protein family was substantially elevated in prostate tumor samples, whereas DTNBP1 and DBNDD2 gene expressions were not." (PMID 37569304, 2023).
squamous cell carcinoma (1 paper, 2022). A carcinoma arising from squamous epithelial cells. "The novel freckles-associated variant rs35415928 in SPATA33 serves as a strong eQTL for several genes in both skin tissue (sun-exposed and no-sun-exposed) and fibroblasts, showing the strongest association with DBNDD1, a gene involved in tanning ability and squamous cell carcinoma." (PMID 36035146, 2022).
tumor (3 papers, 2023 to 2026). "In the HPA database, we observed protein expressions of DBNDD1 in PCa patients using IHC staining, along with clinicopathological data such as patient ID, age, and gender in normal and tumor tissue samples." (PMID 37569304, 2023). "After identifying the DBNDD1 transcriptomic level, we investigated relationships of DBNDD1 gene expression, with corresponding tumor levels of patients and disease prognostication in PRAD, LIHC, and LUAD." (PMID 37569304, 2023). "DBNDD1 gene expression was significantly elevated in PRAD, LIHC, and LUAD tumor tissues compared with normal tissues based on datasets of the TNM plot and GEPIA-based tool." (PMID 37569304, 2023). "We found that DBNDD1 expression was positively correlated with the AR in normal prostate tissues but not significant in tumor prostate tissues." (PMID 37569304, 2023). "E2F3 was negatively correlated with DBNDD1 expression in normal prostate tissues but showed no significance in tumor tissues." (PMID 37569304, 2023).
cancer (2 papers, 2019 to 2023). A tumor composed of atypical neoplastic, often pleomorphic cells that invade other tissues. "Using various databases, we can determine that DBNDD1 gene expression was elevated in numerous types of cancer, and it was associated with prognosis and immune infiltration in PCa patients." (PMID 37569304, 2023). "Our preliminary results revealed that expression of the DBNDD1 gene was significantly affected by sample type, cancer stages, and promoter methylation levels of different cancers such as PRAD, LIHC, and LUAD." (PMID 37569304, 2023). "We performed a pan-cancer analysis with representative genes encoding dysbindin-1, dysbindin-2, and dysbindin-3, including the DTNBP1, DBNDD2, and DBNDD1 genes, respectively." (PMID 37569304, 2023). "We determined that the highest genetic alteration frequency of DBNDD1 in PRAD was roughly 5% compared with other types of carcinoma." (PMID 37569304, 2023). "Moreover, DBNDD1 was observed to be highly expressed in a group of cancer-involved factors, including the G2M checkpoint, mitotic sister chromatid segregation, and mitotic spindle assembly checkpoint signaling." (PMID 37569304, 2023). "Compared with other types of cancer, PRAD exhibited the highest genetic change frequency of DBNDD1, at approximately 5%." (PMID 37569304, 2023).
DBNDD1 also shares sentences with these, for which no sentence is quoted: anemia (1 paper); atherosclerosis (1); bone marrow failure (1); diabetes (1); Fanconi anaemia (1); gastric cancer (1); Insulin resistance (1); oculocutaneous albinism (1); Parkinson disease (1); prostate adenocarcinoma (1); pulmonary fibrosis (1).